CT45A1 (cancer/testis antigen family 45 member A1)
Synonyms: CT45-1; CT45.1; CT45
Tractability: PROTAC: ubiquitination databases record sites on it.
Gene: Protein-coding gene on chromosome X (135,713,639 to 135,723,539, forward strand). Ensembl gene ENSG00000268940.
Subcellular location: Nucleus
Subcellular location (Human Protein Atlas): Nucleoli; Nucleoplasm
Gene Ontology:
Molecular function: protein binding
Cellular component: nucleus
Homologues: Orthologues: rat Ct45a9 (29% identical), mouse Ct45a (28% identical), Caenorhabditis elegans ints-6 (16% identical), Drosophila melanogaster IntS6 (16% identical). Paralogues in human: CT45A3 (99% identical), CT45A5 (99% identical), CT45A6 (99% identical), CT45A7 (99% identical), CT45A2 (98% identical), CT45A8 (98% identical), CT45A9 (98% identical), CT45A10 (94% identical), SAGE1 (35% identical), INTS6L (30% identical), INTS6 (25% identical).
Diseases named in the same sentence as CT45A1 in open-access papers:
CT45A1 is named in the same sentence as 22 diseases in open-access papers, as found by Europe PMC text mining. Sharing a sentence is not in itself a finding about the gene and the disease. The quoted sentences say what the papers report.
breast carcinoma (12 papers, 2014 to 2025). "CT45A1 overexpression in breast cancer cells promoted epithelial‐mesenchymal transition, migration, and invasion through activating the ERK and CREB signalling pathways." (PMID 40638546, 2025). "CT45A1 is a cancer/testis antigen family 45 member A1, which has the ability to promote tumorigenesis and metastasis in osteosarcoma and breast cancer." (PMID 35651938, 2022). "It had been reported that the family member CT45A1 in breast cancer and lung cancer can act as a proto-oncogene to trigger tumorigenesis and cancer metastasis." (PMID 31570735, 2019). "In this regard, CT45A1 is a potent inducer of the expression of the EMT master gene Twist1 in breast cancer and thereby promotes tumor invasion, and metastasis." (PMID 29361914, 2018). "A recent study also showed that over-expression of CT45A1, CT antigen in breast cancer cells selectively enhanced the expression of pro-EMT gene, including TWIST1, ALDH1A1." (PMID 27658496, 2016). "Studies have shown that overexpression of CT45A1 in breast cancer cells significantly upregulates several oncogenic and metastatic genes, indicating that CT45A1 may be a promising biomarker for targeted tumor therapy." (PMID 35659630, 2022). "CT45A1 was shown to work as an oncogene and drive tumorigenesis in breast cancer." (PMID 29190970, 2017). "Mechanistically, CT45A1 activates the ERK and CREB signaling pathways and promotes invasion in breast cancer and lung cancer." (PMID 39322998, 2025).
ovarian carcinoma (11 papers, 2019 to 2025). A malignant neoplasm originating from the surface ovarian epithelium. "Aberrant CT45A1 overexpression is also closely associated with the poor prognosis of malignant tumors, such as ovarian cancer." (PMID 37924456, 2024). "The CCT4 up-regulation and PRAME mutations were correlated with a good prognosis for ovarian cancer, while higher levels of GAGE2A and CT45A1 mRNAs were correlated with a poor prognosis for ovarian cancer patients." (PMID 37835834, 2023).
lung carcinoma (8 papers, 2019 to 2025). "Convincingly, CT45A1 silencing suppresses the proliferation, metastasis and invasion of lung cancer cells by diminishing the ERK/CREB signalling pathway." (PMID 35574342, 2022). "Silencing of CT45A1 in lung cancer cells inhibited tumor cell proliferation, invasion and metastasis." (PMID 35651938, 2022). "As the internalization of NK cells by cancer cells enhances anticancer drug resistance in lung cancer, we cannot exclude the possibility that NK cell internalization enhances resistance to NK cell killing in CT45A1‐expressing MSI‐H CRC cells during the cytotoxic assay." (PMID 39322998, 2025).
osteosarcoma (3 papers, 2021 to 2025). A usually aggressive malignant bone-forming mesenchymal neoplasm, predominantly affecting adolescents and young adults. "We found that CT45A1 was a risk factor in osteosarcoma because that CT45A1 overexpression suggested poorer prognosis in osteosarcoma patients and was closely with clinical pathological grade and metastasis of osteosarcoma." (PMID 34172717, 2021). "Bioinformatics analysis showed us that CT45A1 was associated with the prognosis of osteosarcoma." (PMID 34172717, 2021). "In this research, we found that CT45A1 overexpression could promote the translocation into nucleus of β-catenin and activate β-catenin pathway suggesting that CT45A1 may be a novel gene causing metastasis of osteosarcoma cell via increasing EMT-related proteins in osteosarcoma cells." (PMID 34172717, 2021). "CT45A1 interacts with the TCF4/β‐catenin complex to promote the metastasis of osteosarcoma cell lines." (PMID 39322998, 2025). "We also revealed that CT45A1 promoted the activation of β-catenin and induced metastasis of osteosarcoma." (PMID 34172717, 2021). "Based on our results, the overexpression of CT45A1 significantly promoted the proliferation and metastasis of osteosarcoma cells in vitro and in vivo." (PMID 34172717, 2021). "In this paper, we firstly revealed the function and possible network of CT45A1 in osteosarcoma metastasis." (PMID 34172717, 2021). "Whereas patients with poor prognosis showed high expression levels of CT45A1, patients with lower expression of CT45A1 had prolonged survival, thereby suggesting that CT45A1 is a prognostic marker of osteosarcomas." (PMID 34172717, 2021). "RNA sequencing and immunohistochemistry confirmed that elevated expression of CT45A1 was detected in osteosarcoma, especially in metastatic tissues of osteosarcoma." (PMID 34172717, 2021). "When we examined the CT45A1 expression in normal or osteosarcoma tissues by qRT-PCR we found that CT45A1 was overexpressed in osteosarcoma tissues, compared to the adjacent tissues." (PMID 34172717, 2021). "Here, we first report the functional role of CT45A1, a member of the CT45 gene family, in the carcinogenesis of osteosarcoma." (PMID 34172717, 2021). "Cell tests revealed the positive role of CT45A1 in the proliferation, viability, and metastasis of osteosarcoma cells." (PMID 34172717, 2021). "In cell tests, CT45A1 overexpression was shown to strengthen the proliferation, migration, and invasion abilities of osteosarcoma cells, while silencing CT45A1 markedly elicited the opposite effects in these tests by disrupting the activation of β-catenin." (PMID 34172717, 2021). "The data above suggested that CT45A1 promotes metastasis of osteosarcoma cells both in vitro and vivo through inducing EMT." (PMID 34172717, 2021). "Here, we first report the functional role of CT45A1 in the carcinogenesis of osteosarcoma." (PMID 34172717, 2021). "According to the mechanism underlying these effects, β-catenin which was considered to play an important role in EMT during tumor progression contributed to the mesenchymal changes of osteosarcoma cells with CT45A1 overexpression by regulating the expression of EMT-related proteins." (PMID 34172717, 2021). "Then, the proliferative rate of osteosarcoma cells with different levels of CT45A1 was examined." (PMID 34172717, 2021). "In summary, we identify a novel role of CT45A1 in osteosarcoma." (PMID 34172717, 2021). "Therefore, we first evaluated the role of CT45A1 in the metastasis of osteosarcoma and suggested its potential to serve as a marker for the prognosis of osteosarcoma patients." (PMID 34172717, 2021). "To confirm the role of CT45A1 in osteosarcoma further, we established osteosarcoma cells with CT45A1 overexpression or silencing based on the basal expression of CT45A1 in osteosarcoma cell lines, and the indicated levels of CT45A1 were detected by western blotting assay and qRT-PCR." (PMID 34172717, 2021).
osteosarcoma (continued). "In summary, CT45A1 was correlated with the prognosis and metastasis of osteosarcoma patients and acted as an oncogene in the proliferation, migration, and invasion of osteosarcoma cells which suggested that CT45A1 maybe a possible target for the osteosarcoma diagnosis and treatment." (PMID 34172717, 2021). "Furthermore, osteosarcoma patients with poorer prognosis showed high expression of CT45A1." (PMID 34172717, 2021). "Furthermore, our results suggested that CT45A1 may contribute to the development of osteosarcoma and could be a possible therapeutic target for osteosarcoma patients." (PMID 34172717, 2021).
cervical cancer (1 paper, 2024). A primary or metastatic malignant neoplasm involving the cervix. "In conclusion, CT45A1 is aberrantly overexpressed in cervical cancer patients and overexpression of CT45A1 is closely associated with poor prognosis in these patients." (PMID 37924456, 2024). "More importantly, Kaplan–Meier plots indicated that high expression of CT45A1 was associated with a poor prognosis in cervical cancer patients (kmplot.com)." (PMID 37924456, 2024). "We revealed that CT45A1 was abnormally overexpressed in cervical cancer and overexpression of CT45A1 was closely associated with poor prognosis in the cancer patients." (PMID 37924456, 2024). "The aim of this research was to study the role of CT45A1 in cervical cancer progression and drug resistance, elucidate the mechanisms underlying CT45A1-mediated tumorigenesis and investigate CT45A1 as a biomarker for cervical cancer diagnosis, prognostic prediction, and targeted therapy." (PMID 37924456, 2024). "The role and mechanisms underlying CT45A1-mediated cervical cancer cell tumor growth, invasion, and drug resistance were studied using xenograft mice, cervical cancer cells, immunohistochemistry, RNA-seq, real-time qPCR, Chromatin immunoprecipitation and Western blotting." (PMID 37924456, 2024). "Overexpression of CT45A1 was closely associated with poor prognosis in cervical cancer patients." (PMID 37924456, 2024). "Inhibition of CT45A1 expression by lycorine markedly diminished cisplatin drug resistance and apoptosis resistance in cervical cancer." (PMID 37924456, 2024). "The small molecule lycorine effectively inhibits CT45A1 expression and reduces cervical cancer cell tumorigenesis, neovascularization, cisplatin drug resistance and apoptosis resistance." (PMID 37924456, 2024). "The CT45A1 levels in the tumors from cervical cancer patients were measured using immunohistochemical staining." (PMID 37924456, 2024). "CT45A1 promoted cervical cancer cell tumor growth, invasion, neovascularization, and drug resistance." (PMID 37924456, 2024). "In the current study, we found that CT45A1 levels were notably high in the tumor tissues of human cervical cancer patients." (PMID 37924456, 2024). "Based on these findings, we think that CT45A1 is a potential new target for cervical cancer therapy and explored small molecules that inhibit CT45A1-mediated carcinogenesis." (PMID 37924456, 2024). "Strikingly, the specificity and sensitivity of CT45A1 in the advanced-stage (III-IV) cervical cancer patients reached 98% and 91%, respectively." (PMID 37924456, 2024). "Collectively, these data indicate that CT45A1 enhances tumor growth, neovascularization, and metastasis in vivo and promotes cervical cancer cell tumorigenesis, tube-like structure formation, migration, and invasion in vitro." (PMID 37924456, 2024). "Together, these data suggest that CT45A1 has high tumor specificity and sensitivity and is a new biomarker for the diagnosis and prognostic prediction of cervical cancer." (PMID 37924456, 2024). "Overexpression of CT45A1 was found to boost cisplatin resistance and apoptosis resistance in cervical cancer Siha cells." (PMID 37924456, 2024). "CT45A1 promotes cervical cancer cell tumorigenesis, neovascularization, and drug resistance by activating oncogenic SRC and downstream tumorigenic signaling pathways." (PMID 37924456, 2024). "Conceptually, these findings indicate that inhibition of CT45A1 expression is a new strategy for cervical cancer therapy." (PMID 37924456, 2024). "The result showed that the numbers of tube-like structures in CT45A1-overexpressing cervical cancer Caski cells were more than that of the control Caski cells without CT45A1 expression, suggesting that CT45A1 promotes tumor cells-mediated neovascularization." (PMID 37924456, 2024). "The CT45A1 level of patients with early-stage cervical cancer (I–II) was significantly higher than that of benign uterine myoma patients (p < 0.001)." (PMID 37924456, 2024).
cervical cancer (continued). "This study is the first to unravel the role of CT45A1 in cervical cancer progression and demonstrate that CT45A1 is a new biomarker for cervical cancer diagnosis, prognostic prediction, and therapy." (PMID 37924456, 2024). "CT45A1 levels were notably high in the tumor tissues of human cervical cancer patients compared to the paracancerous tissues (p < 0.001)." (PMID 37924456, 2024). "Collectively, CT45A1 plays an important role in triggering tumorigenesis and is a target for anti-cervical cancer therapy." (PMID 37924456, 2024). "The CT45A1 level of patients with advanced-stage cervical cancer (III-IV) was much higher than that of benign uterine myoma patients (p < 0.001)." (PMID 37924456, 2024). "Next, CT45A1-targeted therapeutics were explored and the small molecule lycorine (MW: 287.31) was found to markedly reduce CT45A1 levels in cervical cancer cells." (PMID 37924456, 2024). "The average survival time was shortened by 2.5 years in the cervical cancer patients with high CT45A1 levels as compared to those with low CT45A1 levels (p = 0.035)." (PMID 37924456, 2024). "This suggests that CT45A1 increases cervical cancer cell cisplatin drug resistance and apoptosis resistance." (PMID 37924456, 2024). "Additionally, co-immunoprecipitation (Co-IP) revealed that CT45A1 was able to directly bind to the SRC protein in cervical cancer cells." (PMID 37924456, 2024). "Together, these data suggest that CT45A1 regulates FN1 gene transcription in cervical cancer cells." (PMID 37924456, 2024). "Additionally, CT45A1 overexpression changed multiple signaling pathways in cervical cancer cells, including the ECM-receptor interaction, focal adhesion, Hippo, and PI3K-AKT signaling pathways." (PMID 37924456, 2024). "Immunohistochemical (IHC) staining revealed that the CT45A1 level in the tumor tissues obtained from 119 cervical cancer patients was markedly higher than that in the paired paracancerous tissues (p < 0.001), with 88% specificity and 62% sensitivity without classification of cancer stage." (PMID 37924456, 2024). "Thus, CT45A1 is a new biomarker for the diagnosis, prognostic prediction, and targeted therapy of cervical cancer." (PMID 37924456, 2024). "Additionally, a colony formation assay showed that CT45A1 increased the cervical cancer cell colony number 2.6-fold, suggesting that CT45A1 increases cervical cancer cell tumorigenesis." (PMID 37924456, 2024). "CT45A1 expression was investigated in cervical cancer patients." (PMID 37924456, 2024). "Moreover, CT45A1 significantly increased the migration and invasion of both cervical cancer Caski and Siha cells; convincingly, silencing of CT45A1 resulted in a significant decrease in HeLa cell migration and invasion, implying that CT45A1 increases cervical cancer cell motility." (PMID 37924456, 2024). "Together, these data indicate that CT45A1-enhanced tumorigenesis, neovascularization, cisplatin drug resistance, and apoptosis resistance can be effectively reduced by lycorine, and lycorine is a new CT45A1 expression suppressor and a novel cervical cancer inhibitor." (PMID 37924456, 2024). "Further investigation revealed that CT45A1 markedly elevated both FN1 mRNA and protein levels in cervical cancer cells." (PMID 37924456, 2024). "In the current study, novel tumorigenic signaling pathways in cervical cancer were identified, including the CT45A1-FN1-SRC-CREB, CT45A1-SRC-ERK, and CT45A1-SRC-YAP/TAZ signaling pathways." (PMID 37924456, 2024). "Convincingly, the SRC-specific inhibitor 6-dimethylamino-2-phenyl-3(2H)-pyridazinone (PP2) markedly suppressed CT45A1-mediated SRC-ERK-CREB activation and inhibited cervical cancer cell migration." (PMID 37924456, 2024). "Immunofluorescence imaging indicated that CT45A1 changed the SRC protein localization from the sub-cellular membrane to the cytoplasm and nucleus in cervical cancer cells." (PMID 37924456, 2024).
cervical cancer (continued). "Immunofluorescence (IF) staining revealed that CT45A1 was overexpressed in the tumor tissues of cervical cancer patients, but not in the paired paracancerous tissues." (PMID 37924456, 2024). "In particular, the expression level of tumorigenic FN1 was increased 14-fold in cervical cancer Caski cells with CT45A1 expression compared to control cells without CT45A1 expression." (PMID 37924456, 2024). "Western blotting revealed that the levels of the YAP/TAZ proteins were notably increased in cervical cancer Siha cells with CT45A1 expression, but did not significantly affect several other signaling pathways." (PMID 37924456, 2024). "However, the role of CT45A1 and other CT45 family members (CT45) in cervical cancer has not yet been reported in the literature." (PMID 37924456, 2024). "The role of CT45A1 in cervical cancer has not yet been described in the literature." (PMID 37924456, 2024).
cervical tumor (1 paper, 2024). "Next, the effect of CT45A1 on cervical tumor growth was examined in xenograft mice." (PMID 37924456, 2024).
colorectal cancer (1 paper, 2025). A primary or metastatic malignant neoplasm that affects the colon or rectum. "CT45A1, a vital driver of the RHO‐ROCK/MLCK‐MLC2 signaling, is found to enhance cancer cell resistance to natural killer (NK) cell killing and generate a protective cell‐in‐cell (CIC) structure in microsatellite instability‐high (MSI‐H) colorectal cancer (CRC) cells." (PMID 39322998, 2025).
ovarian tumors (1 paper, 2023). "A survival analysis using the Kaplan–Meier estimator showed the potential impact of GAGE2A and CT45A1 up-regulation on poor disease-free survival prognosis in ovarian tumors, which was confirmed by a multivariate survival analysis." (PMID 37835834, 2023).